BRCA1 (BRCA1 DNA repair associated)
Diseases named in the same sentence as BRCA1 in open-access papers (continued):
Sharing a sentence is not in itself a finding about the gene and the disease.
serous ovarian cancer (continued). "It has been estimated that approximately half of high-grade serous ovarian adenocarcinoma samples are defective in HR repair pathway, and these HR defects are largely driven by mutations or epigenetic silencing of BRCA1 and BRCA2 genes." (PMID 29254281, 2017). "Somatic and germline BRCA1/2 mutation rates in serous ovarian cancer are 4/46 (8.7%) and 8/46 (17%), respectively." (PMID 27907908, 2016). "The analysis of 47 high grade serous ovarian cancers identified 13 (28%) pathogenic mutations, 8 BRCA1 and 5 BRCA2." (PMID 26745875, 2016). "In the remaining 97 patients diagnosed with serous ovarian carcinoma, pathogenic BRCA1/2 variants were identified in 27 (28%) samples." (PMID 27167707, 2016). "Mutations of the BRCA1/2 genes occur in approximately 20% of high-grade ovarian serous carcinoma and are associated with better survival outcomes." (PMID 27907908, 2016). "In this report, we determined the frequency of somatic and germline BRCA1/2 mutations in serous ovarian carcinoma, the entire coding sequence of these genes was analyzed by next‐generation sequencing." (PMID 27167707, 2016). "We conclude that BRCA1/2 mutations are common in Taiwanese patients with serous ovarian carcinoma and similar to mutation rates in other ethnic groups." (PMID 27907908, 2016). "Tumor Nmut was associated with treatment response and with both PFS and OS in patients with high-grade serous ovarian cancer carrying BRCA1 or BRCA2 mutations." (PMID 24265793, 2013). "The vast majority of inactivating mutations that occur in the BRCA/FA pathway in high-grade serous ovarian carcinomas are found in the BRCA1 and BRCA2 genes." (PMID 23587053, 2013). "Germ line mutations of BRCA1 or BRCA2 genes predispose primarily to high-grade serous carcinoma of the ovary and approximately 16% of high-grade serous carcinoma is associated with germ line BRCA gene mutation." (PMID 20843305, 2010). "The loss of BRCA1 function due to either germline/somatic mutation or epigenetic silencing is observed in most high-grade serous carcinomas of the ovary." (PMID 20843305, 2010). "Furthermore, certain therapies (e.g., olaparib and bevacizumab) offer particularly pronounced benefits for high-grade serous ovarian cancer (HGSOC) patients harboring mutations in the DNA-binding domain (DBD) of BRCA1/2." (PMID 40427638, 2025). "Recently, polyadenosine diphosphate–ribose polymerase inhibitors (PARPi) have revolutionized the therapeutic landscape of BRCA1/2-mutated tumors, especially of BRCA1/2 high-grade serous ovarian cancer (HGSC), taking advantage of HR deficiency through the synthetic lethality concept." (PMID 38544832, 2024). "A retrospective analysis involving 79 cases with BRCA mutations revealed that the most common structural domains of BRCA1 mutations in high-grade serous ovarian cancer (HGSC) were the BRCT (C-terminal) domain (15 cases, 31%) and the DNA Binding Domain (DBD) (13 cases, 27%)." (PMID 39868369, 2024). "In 46% of the platinum-resistant BRCA mutated high-grade serous ovarian carcinomas, reversion mutations in the BRCA1/2 genes could be detected." (PMID 39506058, 2024). "In this study, we compared the results obtained using the next-generation sequencing multi-gene panel to a known germline BRCA1/2 mutational state determined by conventional Sanger sequencing to evaluate the landscape of somatic mutations in high-grade serous ovarian cancer tumors." (PMID 32164585, 2020).
serous ovarian cancer (continued). "Somatic mutation analysis by next-generation sequencing, in addition to germline BRCA1/2 mutation analysis, should become the standard of care for managing women with high-grade serous ovarian cancer to widen the indication of poly (ADP-ribose) polymerase inhibitors." (PMID 32164585, 2020). "Women-specific cancers are a major health issue, particularly those associated with the BRCA1 germline mutation carrier state, which include triple-negative basal breast carcinomas and high-grade serous ovarian carcinomas (referred to as extra-uterine Müllerian carcinomas)." (PMID 32120796, 2020). "They inferred that high grade serous ovarian cancer with mutations in BRCA1/2 may be more sensitive to immune checkpoint inhibitors PD-1 and PD-L1 in comparison with tumors proficient in HR repair." (PMID 31658756, 2019). "Clarke and coworkers also performed an exploratory analysis in a small case series, observing a significant association between intraepithelial TIL and BRCA1 mutations or promoter methylation causing loss of expression, mainly in high-grade serous ovarian cancer." (PMID 31130614, 2019). "Notably, a high expression of miR-622 in BRCA1-deficient high-grade serous ovarian carcinomas correlated with worse outcome after platinum chemotherapy." (PMID 35582723, 2019). "Assessment of BRCA1/2 gene mutation status from formalin-fixed paraffin-embedded (FFPE) tissue became a routine procedure for patients with high-grade serous ovarian cancer, as patients with evidence of such mutations are eligible for therapies including the PARP inhibitor olaparib." (PMID 29453630, 2018). "BRCA1/2 mutations regained clinical attention, as patients with high-grade serous ovarian carcinomas with pathogenic BRCA1/2 mutations displayed improved overall and recurrence-free survival if treated with platinum-based therapy in combination with PARP inhibitors such as olaparib." (PMID 29453630, 2018). "For example, susceptibility to high-grade serous ovarian cancer (HGSOC) is driven by mutations in genes that are involved in DNA double strand break repair (BRCA1, BRCA2, BRIP1, RAD51D and RAD51C), and as a consequence these tumors are highly genomically unstable." (PMID 28881617, 2017). "In conclusion, BRCA1/2 mutations are common in Taiwanese patients with serous ovarian carcinoma." (PMID 27907908, 2016). "Thus, our data indicates that loss of BRCA1 protein is associated with serous ovarian cancer progression." (PMID 24752797, 2014). "The total number of synonymous and non-synonymous exome mutations (Nmut), and the presence of germline or somatic mutation in BRCA1 or BRCA2 (mBRCA) were extracted from whole-exome sequences of high-grade serous ovarian cancers from The Cancer Genome Atlas (TCGA)." (PMID 24265793, 2013). "In fact, long survival in high-grade serous ovarian cancer, when it is observed, may be attributable to mutation in either BRCA1 or BRCA2 when these genotypes are coupled with a high tumor Nmut." (PMID 24265793, 2013). "Furthermore, on the basis of current literature, the cancers in women with BRCA1 mutations appear to be a reasonable model for sporadic serous ovarian cancers." (PMID 19636370, 2009). "Further studies will likely elucidate whether secretory epithelial cells of the tubal fimbria are the primary cell of origin of BRCA1-associated and/or sporadic serous ovarian carcinomas." (PMID 20046879, 2009).
serous ovarian cancer (continued). "For example, BRCA1 mutation carriers appear to predispose to serous ovarian cancers; mutations in the PTEN tumour suppressor gene are more associated with endometrioid ovarian cancers; and K-ras mutations are more common in mucinous tumours than in either serous of endometrioid subtypes." (PMID 18219286, 2008). "High grade serous ovarian cancers are associated with BRCA1 or BRCA2 mutations." (PMID 18208621, 2008). "Hence, inhibition of energy metabolism might constitute a useful strategy to target BRCA1-deficient high grade serous ovarian cancer, a type of tumor characterized by frequent BRCA1 loss." (PMID 35432218, 2022). "Moreover, HR-proficient tumors showed a lower PD-L1 expression on the surface of intraepithelial and peritumoral immune cells compared to the BRCA1/2-mutated tumors, supporting a link between BRCA1/2-mutation status, immunogenicity, and improved survival in high grade serous ovarian cancer." (PMID 31130614, 2019). "Signature 5 was linked to BRCA1/2 copy number loss and exhibited characteristics akin to the HRD signature found in high-grade serous ovarian cancer (HGSOC)." (PMID 40422510, 2025). "Targeted therapies, such as PARP inhibitors, show promise for treating BRCA1/2-mutated cancers, including TNBC and high-grade serous ovarian cancer." (PMID 40710012, 2025). "This study explored the impact of vaginal microbes, metabolites, and METTL1-mediated m7G modification of BRCA1 mRNA on High-Grade Serous Ovarian Cancer (HGSOC)." (PMID 41430564, 2025). "A retrospective cohort study of 474 BRCA1/2 carriers with high-grade serous ovarian cancer also revealed a significantly higher average age at diagnosis for BRCA2 versus BRCA1 mutation carriers (58.4 years vs. 53.3 years, P = .001)." (PMID 40303993, 2025). "Significant improvements in testing rates were reported in patients with high-grade serous ovarian cancer after implementation of reflex BRCA1/2 tumor testing." (PMID 40323485, 2025). "Homologous recombination deficiency (HRD) and sensitivity to PARP inhibitors are key determinants of therapeutic response in high-grade serous ovarian cancer (HGSC), yet predictive biomarkers beyond BRCA1/2 mutations or genomic HRD scores remain inadequate." (PMID 41034557, 2025). "In contrast, the BRCA1/BRCA2 GDH patient is a 44-year-old female with high-grade serous ovarian cancer at clinical stage FIGO IIIC, tolerated chemotherapy well." (PMID 40777133, 2025). "Genetic counselling and germline testing for BRCA1/2 is considered standard of care for all patients diagnosed with high-grade serous ovarian carcinoma (HGSOC)." (PMID 41300712, 2025). "Background/Objectives: Access to genetic counselling and BRCA1/2 germline testing is standard of care for patients with high-grade serous ovarian carcinoma (HGSOC)." (PMID 41300712, 2025). "Women (n = 45) with high-grade serous ovarian cancer underwent genetic counseling and DNA sequencing for BRCA1 and BRCA2 genes." (PMID 38641594, 2024). "BRCA1 methylation was also detected in 14% of the OC patients (p = 0.011), 19.4% of patients aged <55 years (p = 0.0007), and 23.4% of high-grade serous ovarian cancer (HGSOC) patients." (PMID 38542081, 2024). "The patient initially presented with a BRCA1 mutant (BRCA1:c.3190delCTTG) high grade serous ovarian cancer and had initial debulking surgery before receiving standard of care platinum-based chemotherapy." (PMID 37491606, 2023).
serous ovarian cancer (continued). "In high-grade serous ovarian carcinoma (HGSOC), PARP inhibitors are particularly sensitive to HGSOC with mutations in BRCA1 or BRCA2 (BRCA1/2)." (PMID 37324006, 2023). "The Cancer Genome Atlas (TCGA) project has revealed the distribution of patients with BRCA1/2 mutations and/or HRD in ovarian serous carcinoma based on molecular profiling." (PMID 35676859, 2023). "Epigenetic inactivation of BRCA1 through promoter hypermethylation occurs in approximately 15% of TNBCs and 11% to 15% of serous ovarian cancers." (PMID 35681784, 2022). "The carriers of BRCA1 and BRCA2 PVs are specifically susceptible to develop high-grade serous ovarian cancer, with a median age of onset at about 51 and 61 years, respectively." (PMID 36010882, 2022). "Although the exact relationship between DYNLL1 and the 53BP1 axis is still unclear, loss of DYNLL1 was associated with PARPi resistance in a panel of patient-derived BRCA1-mutant high-grade serous ovarian cancer lines." (PMID 35681784, 2022). "MiR-182, a BRCA1 negative regulator, is significantly overexpressed in high-grade serous ovarian carcinoma, which results in a significant reduction in BRCA1 expression." (PMID 35328651, 2022). "In this study, we addressed in a series of 51 high grade serous ovarian cancer (HGSOC) patients the correlation between BRCA1/2 genotype and their survival, in accordance with the functional regions of the proteins." (PMID 34898566, 2021). "Previously, we showed that a conversion of hypermethylated to wild‐type (unmethylated) BRCA1 promoter frequently takes place in high‐grade serous ovarian cancer upon recurrence." (PMID 34601813, 2021). "Germline BRCA1 and BRCA2 mutations are present in 14–15% of EOCs and up to 22.6% of high-grade serous ovarian cancers." (PMID 35008360, 2021). "In high-grade serous ovarian cancer (HGSOC), pathogenic germline variants and somatic BRCA1/2 mutations can be found in 17–25% of patients, and 18–30% of all BRCA1/2 variations are somatic in origin." (PMID 34711195, 2021). "This study aimed to evaluate the efficacy of the triplet combination of these drugs in BRCA1-driven high-grade serous ovarian carcinomas (HGSOCs)." (PMID 33536037, 2021). "We retrospectively reviewed the medical records of 169 high-grade serous ovarian cancer patients who underwent a germline BRCA1/2 test and received three cycles of NAC at the Yonsei Cancer Center from 2006 to 2018." (PMID 32131779, 2020). "All patients had diagnosis of high grade serous ovarian cancer (HGSOC), three harbored a germinal BRCA1 mutation (gBRCA1) and one had a somatic mutation (sBRCA1)." (PMID 31850198, 2019). "In approximately 11% of high-grade serous ovarian cancer, BRCA1 promoter methylation is an important somatic driver." (PMID 35582723, 2019). "For example, 50% of high-grade serous ovarian cancers (HGSOC) exhibit defective DNA repair by inactivation of the homologous recombination due to germline and somatic mutations in BRCA1 (11%), BRCA2 (9%) and promoter hypermethylation of BRCA1 (10%)." (PMID 35582723, 2019). "A recent review article discusses the results of clinical trials and the relation between BRCA1/2 and PARPi in serous ovarian carcinomas." (PMID 29882921, 2018). "BRCA1 promoter hypermethylation has been described previously in primary high-grade serous ovarian cancer, methylation rates ranging from 10-89%." (PMID 29137324, 2017). "In high-grade serous ovarian cancer (HG-SOC), the most common subtype, BRCA1/2 germline and somatic mutations are frequent (17-25%), with somatic mutations representing 18-30% of all BRCA1/2 mutations." (PMID 28525389, 2017).
serous ovarian cancer (continued). "TCGA (The Cancer Genome Atlas) analyses showed that the BRCA1 and BRCA2 mutations in 22% of the high-grade serous ovarian cancer samples triggered a wide range of aberrations in DNA damage repair pathways, such as homologous repair pathway." (PMID 28187748, 2017). "Accordingly, in a thorough analysis of 489 high-grade serous ovarian cancer samples, the TCGA did also fail to show an impact on OS for BRCA1 methylated tumors." (PMID 29137324, 2017). "In 2014, Olaparib was approved as a mono-therapy for maintenance in women with BRCA1/2 mutant, platinum-responsive, high-grade serous ovarian cancer." (PMID 27902462, 2016). "Approximately 50% of high grade serous ovarian cancers (HGSOCs) harbor genetic and epigenetic alterations in gene members of the homologous recombination (HR) DNA repair pathway, most commonly in BRCA1 and BRCA2 genes." (PMID 26871470, 2016). "High-grade serous ovarian cancer (HGSOC) is the most common histologic subtype, and the role of germline BRCA1/2 mutation in predisposition and prognosis is established." (PMID 27242959, 2016). "The heterogeneity of the detected mutations confirms the necessity of simultaneous analysis of BRCA1/2 genes in all patients diagnosed with serous ovarian carcinoma." (PMID 27167707, 2016). "The aim of this study was to identify the frequency and spectrum of germline and somatic BRCA1/2 alterations in a group of Polish patients with ovarian serous carcinoma." (PMID 27167707, 2016). "TCGA analysis showed that the BRCA1 and BRCA2 mutations in 22 % of the high grade serous ovarian cancer (HGS-OvCa) samples triggered a wide range of aberrations in DNA damage repair pathways, such as poly (ADP-ribose) polymerase inhibitors (PARPi)." (PMID 26490766, 2015). "Out of the 20 BRCA1/2 positive patients, 17 were diagnosed with ovarian serous adenocarcinoma (85 %), whereas the other three with adenocarcinoma endometroides (15 %)." (PMID 25366421, 2015). "In this study, an analysis of 218 high-grade serous ovarian cancer cases with wild-type BRCA1/2 revealed a BRCA1/2-directed miRNA signature model." (PMID 25537514, 2015). "The best documented differences are found between Serous Ovarian Carcinomas bearing a germline BRCA1 mutation, which in most cases show increased sensitivity to platinum-based chemotherapy, and sporadic SOC devoid of BRCA1 mutations, which respond poorly." (PMID 26334103, 2015). "BRCA1 hypermethylated serous ovarian adenocarcinomas also displayed a clinical course that was more similar to BRCA1 wild type than BRCA1 mutant tumours." (PMID 23341493, 2013). "The foundation of this study is a synthesis of data from published studies describing occult serous ovarian cancers discovered during prophylactic bilateral PBSO in BRCA1 women." (PMID 19636370, 2009). "In a study by George and colleagues using gene expression and copy number analysis in a cohort with high-grade serous ovarian cancer, tumors with BRCA1 alterations harbored significantly increased intra-epithelial T-cell infiltration compared to BRCA2-mutated samples." (PMID 40426860, 2025). "In high-grade serous ovarian cancer (HGSOC) (III and IV), dynamic analysis of ctDNA for BRCA1/2 reverse mutations or mutations in BRCA1 and TP53BP1 could predict response to PARP inhibitor therapy." (PMID 40076521, 2025). "Moreover, BRCA1/2 CNV detection using ddPCR has been performed to investigate high-grade serous ovarian cancer patient-derived cell line models." (PMID 40725150, 2025).